ATM (ATM serine/threonine kinase)
Diseases named in the same sentence as ATM in open-access papers (continued):
Sharing a sentence is not in itself a finding about the gene and the disease.
breast cancer (continued). "ATM is a serine-threonine kinase that is known to be associated with risk of breast cancer through its regulatory effects on the cellular response to DNA DSB." (PMID 29433565, 2018). "The contribution of mutations detected in the ATM gene to the development of breast cancer needs further detailed study." (PMID 29678143, 2018). "Our findings collectively indicated that ATM gene was a candidate gene in susceptibility to breast cancer in Han Chinese." (PMID 29691986, 2018). "Epidemiological studies on A-T families showed that heterozygous ATM deleterious variant carriers (hereafter referred to as HetAT) are also at increased risk of other cancer types, notably of breast cancer (BC) in female relatives." (PMID 29665859, 2018). "The ATM variant rs1800054 (p.S49C) has recently been implicated as associated with a slightly increased risk for breast cancer (OR 1.08 (C.I .95–1.22) for heterozygotes, 1.44 (.39–5.32) for homozygotes." (PMID 28591191, 2017). "As some studies have suggested, the AA genotype of ATM rs189037 increases the risk of oral and breast cancer." (PMID 29246212, 2017). "ATM was reported to promote abnormal proliferation of breast cancer–associated fibroblasts through maintaining intracellular redox homeostasis and activating the PI3K–Akt, MEK–ERK, and Wnt/β-catenin signaling pathways." (PMID 29371928, 2017). "A recent study had identified an association between an ATM haplotype and breast cancer risk in BRCA1 mutation carriers with a false discovery rate-adjusted p value of 0.029 for overall association of the haplotype." (PMID 27796716, 2017). "ATM is also an intermediate-risk breast cancer susceptibility gene, with rare heterozygous variants being associated with increased risk of developing the disease." (PMID 27796716, 2017). "Certainly, variable expression of biomarkers including ATM in cancer-associated stromal tissues have been observed, and higher levels are associated with aggressive characteristics of breast cancer." (PMID 28418844, 2017). "Most pathogenic mutations were in genes with an established breast cancer risk (ATM, BRCA1, CHEK2, and PALB2)." (PMID 28281021, 2017). "It was reported that miR-181a and miR-181b were upregulated in aggressive breast cancers, and their expression level inversely correlates with ataxia telangiectasia mutated (ATM) levels and DNA damage repair." (PMID 29109913, 2017). "Although several studies have assessed the role of the most common ATM variants in breast cancer susceptibility, the results obtained are inconsistent." (PMID 27796716, 2017). "In particular, ATM is considered a moderate risk or moderate penetrance breast cancer susceptibility gene." (PMID 27884168, 2016). "A total of seven individuals with ATM variants were identified, 5/65 (7.7 %) in breast cancer cases of familial breast and/or ovarian cancer and 2/69 (2.9 %) in breast/thyroid cancer." (PMID 27599564, 2016). "ATM allelic variants were reported to be associated to hereditary breast cancer in 94 Chilean women." (PMID 27557076, 2016). "Another study reported DNA methylation aberrations at an intragenic region of ATM to be associated with increased risk of breast cancer (increased risk for women in the upper quartile, OR 1.89; 95% CI 1.36–2.64; P = 2x10-4)." (PMID 27902704, 2016).
breast cancer (continued). "Initially, epidemiological studies on relatives of A-T patients revealed a two to fivefold increased in the risk of breast cancer for female obligate ATM carriers." (PMID 27599564, 2016). "Anti-ATM antibody ab32420 identified ATM loss or reduction in 616 of 1183 (52%) and ATM high in 567 of 1183 (48%) breast cancers and ATM loss or reduction was associated with poor survival in estrogen receptor negative breast cancer." (PMID 27259260, 2016). "ATM, in which biallelic mutations cause ataxia-telangiectasia (AT), was also suspected to be a breast cancer susceptibility gene in carriers because of an increased breast cancer incidence among relatives of AT patients." (PMID 27716388, 2016). "CD44+/CD24−or low cells isolated from breast cancer cell lines and breast cancer patient specimens were radioresistant, and this resistant phenotype was associated with ATM signaling activation." (PMID 26682001, 2016). "We also showed that reduced ATM expression is associated with poor clinical outcome in early stage breast cancer." (PMID 27741524, 2016). "The patient (ID, NCCH-16) who carried a nonsense mutation in ATM had a personal history of breast cancer and ureter cancer." (PMID 27732944, 2016). "Additional breast cancer susceptibility genes including ATM and CHEK2 also require prospective data to provide the evidence-base for clinical decision making around risk management/reduction and treatment options." (PMID 27099641, 2016). "In the present study, we investigated the frequency and spectrum of ATM mutations in a series of sporadic breast cancers and controls from the Brazilian population." (PMID 25625042, 2015). "Our study bolsters evidence for previously claimed ATM/ATR associations with breast cancer with observations of 4 ATM and 4 ATR truncations in breast cancer cases." (PMID 26689913, 2015). "DNA samples from a series of 100 breast cancer patients (tumor and normal tissues) and 100 control individuals were screened for ATM gene mutations." (PMID 25625042, 2015). "The CHEK2, TGFβ1, CASP8 and ATM genes belong to the ‘low to moderate-risk’ breast cancer susceptibility genes." (PMID 26124080, 2015). "Seventeen of the ATM variants were detected in DNA samples from both breast cancer patients and the control population and were, thus, classified as polymorphisms." (PMID 25625042, 2015). "Women heterozygous for ATM mutations have an estimated relative risk of developing breast cancer of 3.8." (PMID 25625042, 2015). "The limitations of the present study are the small number of samples and low sensitivity of the methodology; although, we identified several ATM polymorphisms in both breast cancer patients and the control population." (PMID 25625042, 2015). "We identified MRE11A nonsense (p.G148X) or ATM frameshift (p.I2629fs) mutations in probands who developed breast cancer." (PMID 26436112, 2015). "Loss of the wild-type allele of the ATM gene has also been reported in tumors of individuals with familial breast cancer and early-onset breast cancer." (PMID 25625042, 2015). "Germline mutations in ATM have also been associated with a moderately increased risk for breast cancer and pancreatic cancer." (PMID 26506520, 2015). "Seven unique DNA sequence variants were observed exclusively in samples from breast cancer patients and were classified as potential ATM mutations." (PMID 25625042, 2015). "ATM-heterozygous germline mutations were shown to contribute to breast cancer, non-Hodgkin’s lymphomas and B-cell chronic lymphocytic leukemia, while ATM-homozygotes develop lymphoma and leukemia." (PMID 26504519, 2015).
breast cancer (continued). "An increased relative risk of breast cancer was identified for female A-T heterozygotes; while, the proportion of sporadic breast cancers in the general population that is due to ATM mutations remains controversial." (PMID 25625042, 2015). "The aim of the present study was to investigate the frequency and the spectrum of ATM mutations in a series of sporadic breast cancer and control samples from the Brazilian population." (PMID 25625042, 2015). "ATM siRNA and miR-18a overexpression caused reduction of homologous recombination and DNA repair in breast cancer cells, making them more sensitive to ionizing radiations." (PMID 24616890, 2014). "It has been estimated that heterozygotes, with ATM mutations that are present in as many as 1% of the total AT population are exposed to an associated risk of the development of breast cancer that is three-to-five-fold greater than the rest of the people." (PMID 25247188, 2014). "Some domestic studies found that ATM rs189037 A allele poorly predicted the outcome of lung cancer and was a risky biomarker of breast cancer in Taiwanese Females." (PMID 25386189, 2014). "Cancer predisposition among AT carriers has revealed that the high rate of malignancy, in particular in breast cancer, is frequently associated with ATM heterozygosity." (PMID 25247188, 2014). "Although this is a novel result in PCa, a large variety of distinct ATM mutations and variants exist among breast cancer patients, and some of them can contribute to the etiology and progression of the malignancy." (PMID 25540025, 2014). "One of the important genes that we have shown to be differentially expressed in the WBC from the carriers and breast cancer patients is ATM, which is a risk factor for breast cancer." (PMID 25403427, 2014). "Heterozygous carriers of certain mutations in ATM also have a moderate risk of developing breast cancer." (PMID 24792170, 2014). "It is proposed that ATM mutation heterozygotes have a 2-fold higher breast cancer risk compared to the general population." (PMID 23586058, 2013). "Recently, we have developed a straightforward, rapid, and inexpensive test to unambiguously diagnose A-T heterozygotes that would allow an easy recognition of breast cancer patients carrying monoallelic ATM germline mutations." (PMID 24252502, 2013). "More recent epidemiological studies have shown that ATM mutations, which cause ataxia telangiectasia in the homozygous state, are also breast cancer susceptibility alleles in heterozygous carriers." (PMID 23741392, 2013). "The ataxia telangiectasia mutated (ATM) kinase is a key DDR protein whose heterozygous germline mutation is a moderate–risk factor for developing breast cancer." (PMID 24252502, 2013). "Our integrated analysis of miRNA and mRNA expression allows us to gain a better understanding of the signaling involved in breast cancer predisposition and suggests a mechanism for the breast cancer-prone phenotype seen in ATM-deficient patients." (PMID 23741392, 2013). "- ATM: It has been known for long that blood relatives of patients with the neurodegenerative disorder Ataxia-Telangiectasia (A-T) face an increased breast cancer risk." (PMID 24025454, 2013). "Currently, no germline mutations have been found in the Chinese population, and only a small number of ATM SNPs have been reported as risk factors for breast cancer." (PMID 23318652, 2013). "Although A-T heterozygotes are usually asymptomatic and, overall considered healthy carriers, a link between single copy ATM mutations and a two to five fold risk of breast cancer has been established." (PMID 24252502, 2013). "There are numerous reports investigating the impact of mutations in ATM on side effects in breast cancer patients." (PMID 22537351, 2012). "Ataxia telangiectasia mutated (ATM) gene regulates OX40L expression through miR-125b implicated in breast cancer and heart disease." (PMID 22870213, 2012).
breast cancer (continued). "In contrast to lung cancer, where the ATM rs664677 C allele is protective, in breast cancer, it seems to be associated with an elevated risk." (PMID 22276117, 2012). "The results from a recent meta-analysis investigation of the association between the ATM D1853N polymorphism and breast cancer risk presented evidence consistent with our results." (PMID 22276117, 2012). "Previously, we used data from mutation screening of ATM in breast cancer patients and controls to demonstrate the ability to detect evidence of pathogenicity from both truncating and splice junction variants (T+SJV) and rare missense substitutions (rMS)." (PMID 21244692, 2011). "As in other studies of ATM and breast cancer risk, the most common pathogenic variant in our study was the ATM c.7271T > G (p.Val2424Gly)." (PMID 21787400, 2011). "To refine the risks associated with different classes of ATM variants, and to examine the molecular pathologic characteristics of ATM-positive tumors, we genotyped 76 rare ATM variants in 2,570 breast cancer cases and 1,448 controls." (PMID 21787400, 2011). "Consistent with its function, mutations within ATM or repression of ATM have been found in multiple cancer types, such as breast cancer, pancreatic cancer, myeloma, leukemias and lymphomas." (PMID 21980462, 2011). "It was later shown that a missense mutation, ATM c.7271T > G (p.Val2424Gly), appears to confer a high risk of breast cancer and to act as a dominant negative." (PMID 21787400, 2011). "Since the cloning of the ATM gene in 1995, many case-control studies have carried out mutation screening and single nucleotide polymorphism (SNP) genotyping to clarify the role of ATM genetic variation in breast cancer predisposition." (PMID 21787400, 2011). "We also genotyped all available relatives of breast cancer cases found to carry putative breast-cancer associated ATM variants to estimate their penetrance." (PMID 21787400, 2011). "This is the largest study to date investigating large numbers of rare missense variants in the ATM gene for association with breast cancer risk." (PMID 21787400, 2011). "Recent studies have confirmed that some specific variants in the ATM gene are associated with increased breast cancer (BC) risk." (PMID 21787400, 2011). "In another experiment, we investigated PTX-2-induced cell cycle arrest at G2/M phase in human breast cancer cells via ATM (ataxia-telangiectasia-mutated) and Chk1/2 (checkpoint kinases 1/2)-mediated phosphorylation of Cdc25C." (PMID 22163180, 2011). "To investigate the role of ATM in BC susceptibility, we studied 76 rare sequence variants in the ATM gene in a case-control family study of 2,570 cases of breast cancer and 1,448 controls." (PMID 21787400, 2011). "To date, a number of studies have been performed to investigate the association between the ATM D1853N polymorphism and breast cancer risk, but the evidence regarding the role of ATM as a genetic marker for breast cancer is conflicting." (PMID 20799949, 2010). "Previously, some studies reported that female ATM-heterozygous carriers have an increased risk of breast cancer." (PMID 20799949, 2010). "Results suggest that ATM protein levels are useful for identifying breast cancer patients at high-risk of clinical radiosensitivity." (PMID 20678261, 2010). "In the current meta-analysis, we cumulated the data from nine case-control studies to explore the association between ATM D1853N polymorphism and breast cancer risk." (PMID 20799949, 2010). "ATM mutations are generally considered low risk alleles for breast cancer and clinical radiosensitivity." (PMID 20678261, 2010). "Overall, nine studies involving 4,191 cases and 3,780 controls about ATM D1853N polymorphism and breast cancer susceptibility were available for this meta-analysis." (PMID 20799949, 2010).
breast cancer (continued). "For want of improving risk assessments for breast cancer and radiosensitivity it would therefore be advantageous to establish pathological threshold levels for the ATM protein." (PMID 20678261, 2010). "Breast cancer patients with the combination of radiation treatment and an ATM missense variant resulted in a shorter mean interval to develop a second tumor than patients without radiation treatment and ATM germline mutation." (PMID 20799949, 2010). "Different mechanisms by which ATM heterozygosity contributes to breast cancer pathobiology were proposed, most of which were associated with the expression of dominant negative ATM protein." (PMID 20175908, 2010). "Do ATM protein levels represent a practical biomarker for assessing risk of radiotherapy toxicity or breast cancer?" (PMID 20678261, 2010). "From results reported here we propose a tentative ATM protein threshold of ~55% for high-risk of clinical radiosensitivity for breast cancer patients." (PMID 20678261, 2010). "Crude odds ratios (ORs) and their corresponding 95% confidence intervals (CIs) for ATM D1853N polymorphism and breast cancer risk were calculated using fixed- or random-effects model based on the degree of heterogeneity among studies." (PMID 20799949, 2010). "Breast cancer risk is also influenced by rarer variants that confer moderate breast cancer risks such as ATM, CHEK2, BRIP1 and PALB2." (PMID 20146796, 2010). "Overall our results indicate a role for variation in the ATM gene both for risk of developing breast cancer, and in radiation induced adverse side effects." (PMID 17623063, 2007). "Several epidemiological studies have shown that relatives of patients with ataxia-telangiectasia heterozygotic for an ATM germline mutation have an increased risk of breast cancer." (PMID 17428320, 2007). "For instance, ATM heterozygous carriers have a relative risk of breast cancer of 2.2 compared with the general population and a relative risk of 4.9 for those younger than 50 years of age." (PMID 17428320, 2007). "Individuals heterozygous for ATM mutations have been reported to have an increased risk of malignancy, especially breast cancer." (PMID 17623063, 2007). "The association between any variant in the ATM gene and risk of breast cancer was computed by comparing the 95 cancer free women and the 272 breast cancer patients from Norway." (PMID 17623063, 2007). "Increased breast cancer risk in ATM heterozygote mutation carriers has been previously reported in studies that either inferred obligate carriership or directly tested for gene mutations." (PMID 16622469, 2006). "Three groups have found an association between specific ATM common haplotypes and the risk of breast cancer." (PMID 17132159, 2006). "ATM gene's contribution to breast cancer risk was previously evaluated in the context of high-risk families, in BRCA1/2 mutation carriers, and in average risk populations." (PMID 16622469, 2006). "Screening of the whole coding region of the gene revealed altogether 17 different sequence variants in the ATM gene in the 47 familial breast cancer patients." (PMID 16914028, 2006). "Altogether, these results suggest that possible breast cancer associated ATM mutations are very rare in breast cancer families from Southern Finland." (PMID 16914028, 2006). "The ATM gene has been suspected to be a breast cancer susceptibility locus, due to the presence of breast cancer in A-T families, particularly among ATM heterozygotes." (PMID 17010193, 2006). "The 4258 C→T and 2527 T→C mutations in the ATM gene have been detected in breast cancer patients, but to the best of our knowledge, these mutations have not been reported in A-T patients." (PMID 17132159, 2006). "ATM haplotypes have been also reported to associate with increased breast cancer risk in Korean population; in that study, one coding and four intronic SNPs were used for haplotype construction." (PMID 16914028, 2006).